NF2 (NF2, moesin-ezrin-radixin like (MERLIN) tumor suppressor)
Diseases named in the same sentence as NF2 in open-access papers (continued):
Sharing a sentence is not in itself a finding about the gene and the disease.
schwannoma (continued). "Typical and pathognomonic for NF2′ are bilateral VS and other peripheral or central nervous system lesions such as meningiomas, spinal ependymomas, non-VS schwannomas, and ocular (e.g. cataracts) or cutaneous findings." (PMID 35771312, 2022). "Treating NF2 patients with the mTORC1 inhibitor RAD001 revealed cytostatic effects of delayed growth or stabilization of schwannomas and MN without tumor shrinkage, and the results of AZD2014 therapy remain under investigation." (PMID 33273014, 2021). "The schwannomatosis is characterized by multiple peripheral schwannomas in the absence of other signs of NF2." (PMID 30710876, 2019). "In contrast, many vessels in schwannomas in NF2 patients exhibited strong VEGFRs expression without PDGFR-β-positive pericytes." (PMID 31848332, 2019). "In schwannoma cells lacking NF2, epidermal growth factor receptor tyrosine kinases ErbB2, ErbB3 and EFGR are overabundant on the cell surface, upregulating their downstream targets, thereby driving cell proliferation." (PMID 28821767, 2017). "Although the 4-hit/3-step model accounts for the majority of the tumours in the cases of SMARCB1 mutation-positive schwannomatosis, biallelic inactivation of the NF2 gene is not observed in all schwannomas." (PMID 27921248, 2017). "The development of schwannomas has been reported to be only seen in conditional homozygous NF2 knockout mice, and not in NF2 hemizygous mice." (PMID 28710469, 2017). "In the six negative controls (N1-N6), all of which were NF2-related schwannomas, none or very faint 70-kDa merlin-specific bands were found in short exposure." (PMID 28710469, 2017). "One normal vestibular nerves and six NF2-related schwannomas were also included as the positive and negative controls, respectively." (PMID 28710469, 2017). "This potential necessity for other genetic events to occur to prompt schwannoma formation is further supported by our results from P0-Cre;Nf2fl/fl animals—where nerve injury is not sufficient to induce schwannomas, despite biallelic nf2 gene inactivation." (PMID 27236462, 2016). "From the mouse model and the LOH detection technique applied in this study, we conclude that LOH of the nf2 gene is neither required for initiation nor progression of schwannomas, considering the inherent detection limit of the chosen technique." (PMID 27236462, 2016). "The necessity of bi-allelic Nf2 gene (e.g., due to LOH) for schwannoma development for human individuals is a long-standing clinical hypothesis." (PMID 27236462, 2016). "In the absence of other characteristic NF2 manifestations, the presence/absence of bilateral VS and intra-dermal schwannomas are the main clinical criteria to differentiate Schwannomatosis from NF2." (PMID 25739810, 2015). "The histological and immunohistochemical characteristics of schwannomas in Schwannomatosis and NF2 conditions are very similar, with no single robust identifiable feature serving for diagnostic purposes." (PMID 25739810, 2015). "The hierarchical cluster of deregulated genes showed no major differences at the miRNA level between the schwannomas (included that tumor from a NF2 patient) but showed differences with respect to the controls." (PMID 23776562, 2013). "Importantly, the human-zebrafish copy number loss intersections included all 3 genes whose hereditary mutation is known to predispose individuals to Schwann cell tumors (neurofibromas, schwannomas and MPNSTs) - NF1, NF2 and SMARCB1." (PMID 24009526, 2013). "Although it is thought that effectively all schwannomas require inactivation of the NF2 gene, no reports apart from those studying NF2 protein have confirmed a 100% knock out of both copies of the NF2 gene." (PMID 19545378, 2009). "Non-NF2-related schwannomatosis is characterized by the development of multiple benign schwannomas of the spinal, peripheral and cranial nerves in the absence of intra-dermal schwannomas, ependymomas and ophthalmic features." (PMID 40794298, 2025).
schwannoma (continued). "Despite the clear evidence that nerve sheath tumours in NF2-SWN were ‘schwannomas’ rather than ‘neurofibromas’ with many previous reports of neurofibromas being reclassified on pathology review, the name neurofibromatosis for NF2-SWN still remained in consensus statements." (PMID 41160189, 2025). "However, schwannomas arising from the gall bladder are extremely rare and have never previously been reported in patients with NF2." (PMID 39618887, 2024). "Patients in our scRNA-seq cohort were limited to sporadic VS, and our findings pertaining to the TME composition and SC states may not be generalizable to patients with schwannoma of other sites or patients with syndromic NF2-related schwannomatosis." (PMID 38216553, 2024). "However, many patients and families with schwannomatosis do not have identifiable germline variants in NF2, SMARCB1, LZTR1, CDKN2A, or DGCR8, and efforts have been underway to identify other responsible molecular drivers of schwannoma predisposition." (PMID 37821623, 2023). "Schwannomatosis is characterized by the presence of multiple schwannomas without landmarks of NF2." (PMID 36363549, 2022). "Intradermal schwannomas are characteristic lesions in NF2 and are absent in schwannomatosis." (PMID 35361920, 2022). "As the predominant tumor type in NF2 is the schwannoma (and not neurofibroma), there has been discussion that the more appropriate name for NF2 might be Schwannomatosis Predisposition Syndrome (SPS), merlin type." (PMID 33445724, 2021). "While it has been hypothesized that NF2 mediates schwannoma development through Hippo pathway signaling, no direct evidence has been shown." (PMID 32960816, 2020). "Distinctive plexiform “plaque-like” dermal or subcutaneous schwannomas may be encountered in NF2 which are not seen in the sporadic setting or schwannomatosis." (PMID 31161239, 2020). "Most vessels in schwannomas in non-NF2 patients exhibited slight or negative VEGFRs expression." (PMID 31848332, 2019). "However, a recent study showed that celecoxib failed to prevent the generation of schwannomas in a genetically engineered mouse model of NF2 inactivation, although COX-2 expression was increased in tumors that developed in these mice." (PMID 29587439, 2018). "Using a genetically engineered murine model of NF2, we demonstrate that selective inhibition of COX-2 with celecoxib fails to prevent the spontaneous development of schwannomas or sensorineural hearing loss in vivo, despite elevated expression levels of COX-2 in Nf2-deficient tumor tissue." (PMID 29416648, 2018). "However, only 5% of sporadically occurring schwannomas in patients without NF2 or schwannomatosis exhibit mosaic SMARCB1 expression." (PMID 27921248, 2017). "However, to date there are no FDA-approved therapies that target schwannoma cells directly and reduce morbidity and mortality of NF2 patients." (PMID 28427224, 2017). "Consequently, the studies reporting lower LZTR1 mutation detection rates included a more heterogeneous group of patients whose schwannomas may not have been characterized by biallelic NF2 inactivation." (PMID 27921248, 2017). "The ‘one-hit’ NF2 gene status in schwannomas by our detection tools may not reflect this fact." (PMID 28710469, 2017). "In summary, relevant LOH of the nf2 gene could not be detected in our schwannoma induction model." (PMID 27236462, 2016). "Finally, osteopontin upregulation may contribute to merlin degradation in schwannomas with no apparent genetic (22q LOH and/or mutation) NF2 inactivation." (PMID 23354516, 2013). "NF2-SWN patients develop multiple benign tumors of the nervous system, such as schwannomas, particularly bilateral vestibular schwannomas, without current effective treatments." (PMID 40746735, 2025).
schwannoma (continued). "While neurofibromas may be diagnosed in patients with NF2, they are not clearly associated with this syndrome despite the syndrome’s description as a ‘neurofibromatosis’, in contrast to NF1, and many of the reported neurofibromas likely represent misdiagnosed hybrid schwannoma/neurofibromas." (PMID 31161239, 2020). "Finally, no major differences were observed among tumors of different size, histological type or NF2 status, which suggests that, at the mRNA level, all schwannomas, regardless of their molecular and clinical characteristics, may share common features that can be used in their treatment." (PMID 23354516, 2013). "Schwannomas are benign peripheral nerve sheath tumors (PNSTs) arising from myelin sheaths, with schwannomatosis characterized by multiple lesions without neurofibromatosis type 1 (NF1) or type 2 (NF2) stigmata." (PMID 41970298, 2026). "Furthermore, schwannomas of patients with SMARCB1- and LZTR1-related SWN are phenotypically and histopathologically indistinguishable from schwannomas of patients with NF2-related SWN and sporadic schwannomas." (PMID 40794298, 2025). "Furthermore, some patients with mosaic NF2-related SWN may not develop vestibular schwannomas at all and only present with peripheral schwannomas." (PMID 40794298, 2025).
neurofibromatosis type 2 (247 papers, 2008 to 2026). "Neurofibromatosis type 2 (NF2) is a genetic disorder that affects the nervous system caused by mutations in the NF2 gene located on chromosome 22." (PMID 41454441, 2026). "Schwannomatosis represents a distinctive neurofibromatosis condition which causes multiple schwannomas while sparing vestibular schwannomas together with the other NF2-related features." (PMID 40337438, 2025). "Sporadic CVS are caused by somatic mutation within vestibulocochlear nerve Schwann cells, whereas NF2-related schwannomatosis, formerly neurofibromatosis type 2 or NF2, is caused by systemic mutation in the NF2 gene on 22q12.2." (PMID 41300330, 2025). "Various molecular bases have been reported at different times like Honda suggested that mutations in NF-2 were responsible for schwannomatosis while MacCollin considered schwannomatosis a separate entity for neurofibromatosis." (PMID 40337438, 2025). "Neurofibromatosis type 2 (NF2) is an autosomal dominant disorder caused by mutations in the NF2 gene on chromosome 22q12." (PMID 40737523, 2025). "MNs are a hallmark feature of Neurofibromatosis type 2 (NF2), a genetic disorder characterized by mutations in the NF2 gene and the presence of bilateral vestibular schwannomas." (PMID 41200151, 2025). "NF2-related schwannomatosis (NF2, formerly neurofibromatosis type 2) is a rare, autosomal dominant tumor predisposition syndrome caused by a mutation in the NF2 gene." (PMID 39941885, 2025). "In human medicine, MA can present in two forms: sporadic and neurofibromatosis type 2 (NF2) associated forms." (PMID 40557270, 2025). "Neurofibromatosis 2 is less common than neurofibromatosis type 1 and is triggered by mutations of the NF2 gene in chromosome 22, which encodes the tumor suppressor, merlin, and closely related cytoskeletal ERM proteins (ezrin, radixin, moesin)." (PMID 40940747, 2025). "Previous studies have shown that neurofibromatosis, including NF2, was associated with symptoms of depression and anxiety, higher levels of stress, and lower levels of self-esteem." (PMID 39198186, 2024). "Neurofibromatosis type 2, now termed NF2-related schwannomatosis, caused by a mutation in the NF2 gene, results in the loss of function of Merlin, a tumor suppressor protein, which leads to the overexpression of YAP1 (yes-associated protein 1)." (PMID 39202270, 2024). "The most common mutations are germline NF2 mutations, which are responsible for neurofibromatosis type 2 (NF2)." (PMID 38321548, 2024). "Neurofibromatosis type 2 (NF-2) is a dominantly inherited genetic disorder that results from variants in the tumor suppressor gene, neurofibromin 2 (NF2)." (PMID 39415595, 2024). "Neurofibromatosis type 2 (NF2) is a rare autosomal-dominant neurocutaneous disease resulting from mutations in the NF2 tumor suppressor gene." (PMID 39198186, 2024). "Whereas germline NF2 mutations lead to neurofibromatosis type 2, somatic mutations in the NF2 gene inhibit NF2’s tumor suppressive effects, thereby promoting the formation of various cancerous tumors." (PMID 39796693, 2024). "In the current study, we focused on Merlin, another upstream regulator of Hippo signaling and a classic tumor suppressor whose mutations underlie the human disease Neurofibromatosis Type II (NF2)." (PMID 39116228, 2024). "NF2, which has mutations linked to neurofibromatosis type II, suppresses tumors and activates the Hippo signaling pathway components." (PMID 39594616, 2024). "The diagnosis of neurofibromatosis 2 mainly involves clinical presentation of the associated tumors, family history of NF2, and genetic testing." (PMID 38541874, 2024).
neurofibromatosis type 2 (continued). "Additional proteins mediate the regulation of the Hippo pathway, such as neurofibromin-2 (NF2), a classic tumor suppressor that underlies the autosomal-dominant disorder neurofibromatosis type II." (PMID 40491864, 2024). "SP-EPs affect 18%-53% of patients with neurofibromatosis type 2, with clinical symptoms appearing in less than 20% of cases; 39% of SP-EP patients had NF2 insertion/deletion or nonsense mutations." (PMID 38125233, 2023). "Our patient is a 15-year-old with germline neurofibromatosis Type 2 (NF2) confirmed by pathogenic mutation of c.-854-??46+??deletion." (PMID 36975468, 2023). "Neurofibromatosis Type-2 (NF2) is an autosomal dominant genetic tumour-predisposing condition caused by mutations in the NF2 gene located on chromosome 22q12." (PMID 36950434, 2023). "SP-EPs are more common in individuals with neurofibromatosis type 2 who have germline nonsense and frameshift mutations in the neurofibromatosis type 2 (NF2) gene than in patients with other types of NF2 mutations." (PMID 38125233, 2023). "Neurofibromatosis type 2 is an autosomal-dominant neoplasia disorder caused by mutations in the neurofibromatosis 2 (NF2) gene, encoding a tumour suppressor protein called Merlin." (PMID 36899941, 2023). "Moesin-ezrin-radixin-like protein (Merlin) has a genetic mutation that leads to neurofibromatosis type 2 (NF2)." (PMID 37469419, 2023). "In the rare tumour predisposition syndrome NF2-related schwannomatosis (NF2-SWN)—previously known as neurofibromatosis type 2—pathogenic variants in the tumour suppressor NF2 gene elicit the growth of bilateral vestibular schwannoma (VS)." (PMID 37680691, 2023). "As for the germline mutations of NF2, only very rare reports described the onset of a PM in the context of a type 2 neurofibromatosis." (PMID 35223506, 2022). "Considering the role of the NF2 gene in the regulation of leptomeningeal cell proliferation, patients affected by neurofibromatosis have an increased risk of developing meningiomatosis." (PMID 35892898, 2022). "In the context of cancer, NF2 was consequently initially linked to oncogenesis through this association of NF2 mutations and neurofibromatosis type 2 due to the observed generation of peripheral and central nervous system tumours." (PMID 35119068, 2022). "Neurofibromatosis type 2 is an autosomal dominant tumor-prone disorder mainly caused by NF2 point mutations or intragenic deletions." (PMID 36077416, 2022). "Neurofibromatosis Type 2 (NF2) is a rare tumor disorder caused by pathogenic variants of the merlin tumor suppressor encoded by NF2." (PMID 35875610, 2022). "Astrocytomas are observed very rarely in association with NF2 (Gene Reviews—Neurofibromatosis 2, 2018." (PMID 35332608, 2022). "The association between neurofibromatosis type-2 and spinal ependymoma is well established and somatic NF2 variants are recurrently altered in ependymomas with intraspinal location." (PMID 36008825, 2022). "Neurofibromatosis type 2 (NF2) is a genetic disorder that causes growth of multiple benign tumor types throughout the central and peripheral nervous systems." (PMID 35875610, 2022). "Literature findings indicate that genetic mutations of the NF2 gene associated with neurofibromatosis type II, as well as incomplete tumor resection, are predictors of poor outcomes." (PMID 36479403, 2022). "In the case of the malignant peripheral nerve sheath tumors, it was shown that T-Antigen was binding and inactivating NF2, the putative tumor suppressor protein associated with neurofibromatosis type 2." (PMID 33499370, 2021). "Germline loss of LZTR1, leucine-zipper-like transcriptional regulator 1, is a cause of a type of neurofibromatosis, like NF2." (PMID 33556121, 2021). "In case S12, it was shown by OGM that the partial duplication of NF2 was the cause of the neurofibromatosis of the patient, as the gene was disrupted by the insertion of the duplicated material." (PMID 34946907, 2021).